C12orf60 (chromosome 12 open reading frame 60)
Synonyms: MGC47869
Tractability: Antibody: the Human Protein Atlas places it where antibodies can reach.
Gene: Protein-coding gene on chromosome 12 (14,802,864 to 14,906,586, forward strand). Ensembl gene ENSG00000182993.
Subcellular location (Human Protein Atlas): Cytosol; Nucleoplasm; Plasma membrane; Vesicles
Gene Ontology:
Molecular function: protein binding
Genetic constraint (gnomAD): Loss-of-function variants: 0 observed, 0.27 expected, observed/expected ratio (o/e) 0, 90% interval 0 to 1.87. That is too few expected variants to judge how well the gene tolerates losing a copy. Missense variants: 284 observed, 297.26 expected, observed/expected ratio (o/e) 0.96, 90% interval 0.87 to 1.05. Synonymous variants: 102 observed, 100.12 expected, observed/expected ratio (o/e) 1.02, 90% interval 0.87 to 1.2.
Homologues: Orthologues: macaque C11H12orf60 (93% identical), chimpanzee C12H12orf60 (81% identical), dog C12orf60 (64% identical), pig C12orf60 (64% identical), mouse BC049715 (55% identical), rat C4h12orf60 (51% identical).
Diseases named in the same sentence as C12orf60 in open-access papers:
C12orf60 is named in the same sentence as 1 disease in open-access papers, as found by Europe PMC text mining. Sharing a sentence is not in itself a finding about the gene and the disease.
C12orf60 shares sentences with these, for which no sentence is quoted: Macrocephaly (1 paper).